PTK2 (protein tyrosine kinase 2)
Diseases named in the same sentence as PTK2 in open-access papers (continued):
Sharing a sentence is not in itself a finding about the gene and the disease.
breast carcinoma (continued). "In breast cancer, nobiletin has been found to significantly inhibit the protein tyrosine kinase 2 (PTK2)/SRC/STAT3 angiogenetic signaling pathway, and, consequently, tumor proliferation." (PMID 31354472, 2019). "In this study, the PTK2 mRNA was stable in the breast cancer cells, but the corresponding protein showed an elevation after P1." (PMID 31261642, 2019). "SWI/SNF-related matrix-associated actin-dependent regulator of chromatin subfamily E member 1 (SMARCE1) is known to play an essential role in breast cancer metastasis by protecting cells against anoikis through the HIF1A/PTK2 pathway." (PMID 29728663, 2018). "In accordance with previous research, expression levels of Focal adhesion kinase (FAK/PTK2) are correlated strongly with poor tumor differentiation and significantly associated with HER2 overexpression in breast cancer." (PMID 30577793, 2018). "It has been shown that when PTK2 is blocked, breast cancer cells became less metastatic due to decreased mobility." (PMID 27895661, 2016). "For example, PTK2 activation was detected in circulating tumor cells isolated from 90 % of patients with metastatic breast tumors, implicating a role of PTK2 in breast cancer metastasis." (PMID 27495308, 2016). "This study establishes a novel role of SMARCE1 in regulating metastatic potential of breast cancer cells by promoting survival of detached cells through the HIF1A/PTK2 pathway." (PMID 27495308, 2016). "SMARCE1 plays an essential role in breast cancer metastasis by protecting cells against anoikis through the HIF1A/PTK2 pathway." (PMID 27495308, 2016). "Our study provides evidence suggesting an essential role of SMARCE1-based chromatin remodeling activity in breast cancer metastasis by facilitating HIF1A-mediated PTK2 transcription activation in detached cells under normoxia." (PMID 27495308, 2016). "In this study, we demonstrated that SMARCE1 plays a key role in breast cancer metastasis by protecting breast cancer cells against anoikis through the HIF1A/PTK2 pathway." (PMID 27495308, 2016). "DepMap portal plots using publicly available data derived from human breast cancer cell lines and Gepia2 plots using publicly available tumor samples from patients with breast cancer demonstrated that TNBC subtypes show high expression levels of PTK2 (FAK), EGFR, ITGA5, ITGB1, and STAT3." (PMID 38315147, 2024). "CircRPAP2, a circRNA derived from the host gene RPAP2, is expressed in breast cancer tissues and inhibits the proliferation and migration of breast cancer by competing with the association between the splicing factors SRSF1 and PTK2 pre-mRNA to modify the alternative splicing pattern of PTK2 mRNA." (PMID 35884948, 2022). "Multidimensional analysis was used to evaluate the gene alterations and gene and protein functional networks related to the expression of PTK2 in breast cancer and to explore the relationship between its differential expression and methylation and the ceRNA regulatory network." (PMID 36533074, 2022). "The expression level of PTK2 is closely related to breast cancer progression." (PMID 36533074, 2022). "The next important bottleneck gene, is protein tyrosine kinase 2 (PTK2) which is an enzyme playing crucial roles in cell adhesion, migration and survival and aberrant upregulation of PTK2 in epithelial cells leads to malignancies such as breast cancer." (PMID 35290401, 2022). "PTK2 mRNA expression was relatively high in breast cancer cell lines." (PMID 36533074, 2022). "The construction of a ceRNA network of PTK2 indicates that PTK2 may be involved in a variety of molecular mechanisms in breast cancer." (PMID 36533074, 2022). "In addition, we found that PTK2 methylation at certain CpG sites was correlated with poor prognosis in breast cancer patients, indicating that methylation levels of PTK2 act as a powerful prognostic biomarker." (PMID 36533074, 2022). "The methylation level of the PTK2 gene in breast cancer was higher than that in normal tissue." (PMID 36533074, 2022).
breast carcinoma (continued). "To further evaluate PTK2 expression in breast cancer, we used the UALCAN database for analysis." (PMID 36533074, 2022). "We found that PTK2 expression was higher in breast cancer tissues than in normal tissues." (PMID 36533074, 2022). "A previous study showed that PTK2 activates the survival signaling pathway in breast cancer and may inhibit tumor growth." (PMID 36533074, 2022). "In addition, the identification of the circRPAP2/SRSF1/PTK2 axis provides new insights into the pathogenesis of breast cancer and highlights a novel target for the development of oncotherapeutics." (PMID 35368030, 2022). "Correlation analysis between PTK2 and gene markers of immune cells in breast cancer by TIMER." (PMID 36533074, 2022). "The results suggest that PTK2 is significantly correlated with the prognosis of breast cancer." (PMID 36533074, 2022). "Next, we explored the DNA methylation level of PTK2 in breast cancer." (PMID 36533074, 2022). "Interestingly, breast cancer cells harboring PTK2 copy-gain have shown a high sensitivity to FAK inhibitors toward apoptotic responses." (PMID 33562737, 2021). "PTK2 upregulation is correlated with an aggressive phenotype of breast carcinoma." (PMID 31791326, 2019). "PTK2 gene has been identified as a critical gene in breast carcinoma, too." (PMID 27876019, 2016). "CDH1 inactivation is mutually exclusive to PTK2 activation in breast cancer (p-value = 0.001)." (PMID 26427375, 2015). "Consistent with this hypothesis, breast cancer cell lines grown in monolayer culture frequently express constitutively activated PTK2, whereas normal mammary epithelial cells grown under similar conditions do not." (PMID 16457699, 2005). "Furthermore, 16 possible ceRNA networks related to PTK2 were constructed for breast cancer." (PMID 36533074, 2022). "In addition, we examined PTK2 mRNA expression in breast cancer using RNA-seq data from TCGA." (PMID 36533074, 2022). "Phosphorylation of FAK/PTK2 and its downstream effectors, P130Cas and paxillin, was reduced in defactinib-treated JIMT-1 and MDA-MB-231 breast cancer cell lines compared with DMSO-treated cells." (PMID 41148501, 2026). "Specifically, the most prevalent kinase fusion genes differed by subtype: MED1::CDK12 in HER2+ breast cancer, PTK2::AGO2 in TNBC, and KAT6B::ADK in HR+/HER2‒ breast cancer." (PMID 41213951, 2025). "However, the prognostic value of PTK2 and its potential function remain unclear in breast cancer." (PMID 36533074, 2022). "However, the exact function and mechanism of PTK2 in breast cancer remain unknown." (PMID 36533074, 2022). "Comprehensive bioinformatics analyses based on the molecular taxonomy of breast cancer international consortium (METABRIC) and TCGA databases have assessed the significance of PTK2 expression in breast cancer patients." (PMID 33562737, 2021). "Based in these observations, we included into the analysis of data bases both PTK2 and PTEN, both showing also marked alterations in breast cancer samples (12% and 7%, respectively)." (PMID 32414394, 2020). "Moreover, the mRNA expression levels of the FAK encoding gene (PTK2), FAK phosphorylation as well as the focal adhesion points (FAs) are higher in triple negative breast cancer (TNBC), an aggressive BC type characterised by high metastatic potential." (PMID 32751931, 2020). "To confirm that HIF1A-mediated PTK2 transcription is critical for breast cancer cell to survive anoikis, we examined the effect of HIF1A knockdown on cell sensitivity to anoikis and detachment-induced activation of PTK2, ERK, and AKT." (PMID 27495308, 2016). "This revealed several known kinase targets in breast cancer such as ERBB2, PAK1, RPS6KB1 and PTK2 (refs 16, 17), together with a new candidate kinase target, TLK2." (PMID 27694828, 2016).
breast carcinoma (continued). "Together, these results suggest that activation of PTK2, ERK, and AKT pathways is critical for breast cancer cells to survive anoikis, and SMARCE1 activity is required for the activation of these survival pathways in detached cells." (PMID 27495308, 2016). "Furthermore, among the key proteins in FA pathways, FAK, also known as PTK2, exhibited the most significant impact on the overall survival of TCGA breast cancer patients." (PMID 39287113, 2024). "The functions of PRKAA1, PTK2, and TSC2 in PI3K/signaling governing HER2+ breast cancer development and suppression by PGB-0-ol remain unknown and require further investigation." (PMID 38028209, 2023). "Consequently, to deepen the understanding of PTK2 crosstalk with the immune response, we used the TIMER database to validate the relationship between PTK2 expression and diverse immune signatures in breast cancer." (PMID 36533074, 2022). "There was a significant relationship between overall survival (OS) and relapse-free survival (RFS) of breast cancer patients with PTK2 gene alterations, but not with disease-free survival." (PMID 36533074, 2022). "Survival analysis elaborations performed on invasive breast tumor using fluorescence in situ hybridization (FISH) confirmed that breast cancer patients with both PTK2 and FISH positivity exhibit shorter OS and RFS rates with respect to those with PTK2 and FISH negativity." (PMID 33562737, 2021). "Mechanistic studies indicate that PTK2 deletion in mammary tumor cells reduces the expression/phosphorylation of ERK1/2 contributing to the tumor dormancy in vivo and arrests growth in cultures suggesting PTK2 signaling through ERK-MAPK pathway is required to maintain tumor cell growth." (PMID 22937096, 2012). "Several of these regions contain genes known to be amplified in breast cancer, including ERBB2, EGFR and MYC, while others include genes not previously implicated in breast cancer, including PTK2." (PMID 16457699, 2005). "Likewise, in chromosome 8, arm-level gains of 8q and losses of 8p in human breast cancer SCNAs were further segmented into three amplification peaks involving STK3, MYC, and PTK2 and three deletion peaks involving CSMD1, PSD3, and IDO1 in hg19-aligned CMT SCNAs, respectively." (PMID 32680987, 2020). "Similarly, protein tyrosine kinase 2 (PTK2) (which indicates oncogenic transformation) could also be tracked in MVs derived from MDAMB231 cells, further suggesting that analysis of EV content is an attractive target for diagnostics in breast cancer." (PMID 36045692, 2022). "In addition, we found that the PTK2 mRNA expression levels are significantly higher also in ER+/PR+/HER2- and ER-/PR-/HER2+ breast tumors respect to normal breast tissues, however the TNBC samples displayed the highest expression levels among the different breast cancer phenotypes." (PMID 30728047, 2019). "The amplification of PTK2, MYC, NBN, and RAD21 found prognostic biomarkers independent of breast cancer subtype." (PMID 35494043, 2022).
melanoma (173 papers, 2008 to 2026). A malignant, usually aggressive tumor composed of atypical, neoplastic melanocytes. "Copy-number gain of PTK2 would thus be associated with resistance to anti-PD-1 therapy in melanoma." (PMID 35013211, 2022). "Focal adhesion kinase (FAK, also known as PTK2) was the most differentially activated kinase between NECTIN1-deficient and proficient A375 melanoma cells." (PMID 36229674, 2022). "The lower activation levels of focal adhesion kinase (FAK/PTK2), Rho family proteins (RhoA, Rac1, and Cdc42), and mTORC1 pathway resulted in activation of AMPK pathway and reduced proliferation and metastasis of melanoma cells." (PMID 35328492, 2022). "Furthermore, differential expression analysis revealed upregulation of genes such as PTK2, PRG2, and VEGFA in tumor samples compared to normal skin, alongside downregulation of other ARGs—reinforcing their involvement in melanoma pathogenesis." (PMID 40943183, 2025).
ovarian carcinoma (159 papers, 2007 to 2026). A malignant neoplasm originating from the surface ovarian epithelium. "circ-PTK2 is an important molecule in regulating the pathogenic processes of ovarian cancer via the miR-639 and FOXC1 regulatory cascade." (PMID 34034740, 2021). "PTK2 has been extensively linked with tumor progression, especially in ovarian cancer." (PMID 37206435, 2023). "PTK2 is known to be overexpressed in cancer including 86% of serous ovarian cancer cases, being strongly associated with a poor prognosis, suggesting a tumor-promoting role of this gene in ovarian cancer." (PMID 36077645, 2022). "From The Cancer Genome Atlas (TCGA) data analysis, we found that PTK2 exhibits the highest copy number amplification in ovarian cancer compared to other cancer types." (PMID 38373953, 2024). "In conclusion, this study demonstrates the key role of the NRSN2-AS1/PTK2/β-catenin axis for the first time and explores its potential clinical applications in ovarian cancer." (PMID 37875515, 2023). "Mechanistically, NRSN2-AS1 stabilizes protein tyrosine kinase 2 (PTK2) to activate the β-catenin pathway via repressing MG-53-mediated ubiquitinated degradation of PTK2, thereby facilitating ovarian cancer progression." (PMID 37875515, 2023). "ETS1, a crucial transcription factor produced by the microenvironment in ovarian cancer cells, predicts a poor prognosis and targets PTK2 while promoting graft colonization by increasing FAK transcript levels." (PMID 36407100, 2022). "Decreased PTK2 expression has been reported to have a growth-inhibitory impact, and its knockdown in ovarian cancer cell lines reduced cell viability and anchorage-independent growth." (PMID 36077645, 2022). "According to our study, promising therapies by targeting circ-PTK2 should also be investigated in the future to treat metastatic disease of ovarian cancer." (PMID 34034740, 2021). "Circ-PTK2 expression was significantly higher in the ovarian cancer tissues compared with normal ovary tissues (P < 0.001)." (PMID 34034740, 2021). "We collected 26 ovarian cancer samples and 11 normal ovary samples to analyze the level of circ-PTK2 between ovarian cancer and normal ovary samples using FISH." (PMID 34034740, 2021). "In this study, we found that circ-PTK2 performs an important role in regulating cell migration and invasion in ovarian cancer." (PMID 34034740, 2021). "In this study, we found that angiogenesis was strongly inhibited by knockdown of circ-PTK2, suggesting that circ-PTK2 also promote the progression of ovarian cancer by stimulating angiogenesis." (PMID 34034740, 2021). "Our results demonstrated a regulatory cascade related to circ-PTK2 expression, which potentially correlates to the processes of ovarian carcinoma." (PMID 34034740, 2021). "Spontaneous copy number gains in genes for Kras, Myc, and FAK (Ptk2) in a new murine model (KMF) of ovarian cancer." (PMID 31478830, 2019). "Among the ETS1-regulated genes in metastasizing ovarian cancer cells, protein tyrosine kinase 2 (PTK2) plays a key role in promoting metastasis." (PMID 31640297, 2019). "In terms of PTK2, it is a cytoplasmic protein tyrosine kinase and has an expression in various solid tumors such as ovarian cancer, gastric cancer, and bladder cancer." (PMID 30275981, 2018). "Genetic tumor profiling has revealed both FAK DNA amplification (PTK2 gene at 8q24.3) and elevated FAK mRNA levels in several cancers, including breast and ovarian carcinomas." (PMID 28953264, 2017). "Overexpression of PTK2 in ovarian cancer is significantlyassociated with poorer survival and PTK2 is being investigated as a therapeutic target inxenograft models of ovarian cancer." (PMID 21423607, 2011). "The more activated PTK2, the higher the degree of involvement in cell adhesion and spread, which has guiding significance for the prognosis of multiple cancers, such as colorectal cancer, ovarian cancer and esophageal cancer." (PMID 36158681, 2022).
ovarian carcinoma (continued). "Circ-PTK2 was specifically expressed in the cytoplasm of the ovarian cancer tissue." (PMID 34034740, 2021). "Clinical, in vitro and in vivo evidence strongly suggested that upregulation of HK2 in ovarian cancer was correlated with metastasis and poor survival and mediated migration, invasion and stemness via PTK2/MAPK1/3/MMP9/NANOG/SOX9 signaling cascades in vitro and in a nude mouse model." (PMID 33052246, 2020). "Additional protein kinase that are frequently amplified in cancer include FAK (PTK2, 8q24, in 30% of ovarian cancers), the mTORC2 activator RICTOR (5p13.1) in epithelial malignancies, CDK4 (12q13-15) in sarcomas and glioblastomas, or CDK6 (7q21) in esophageal and stomach cancers." (PMID 31817861, 2019). "PTK2 copy number variation was unique to drug‐sensitive recurrent ovarian cancer." (PMID 29797793, 2018). "Interestingly, in several cancers, including breast and ovarian carcinomas, genetic tumor profiling has revealed both FAK DNA amplification (PTK2 gene at 8q24.3) and elevated FAK mRNA levels." (PMID 28953264, 2017). "Similarly, PTK2 is also amplified in ovarian cancer andmutated in solid tumors." (PMID 21423607, 2011). "Rescue experiments verify the function of the NRSN2-AS1/PTK2/β-catenin axis and the effects of MG53 on this axis in ovarian cancer cells." (PMID 37875515, 2023). "Using a new in vivo-evolved murine ovarian cancer model termed KMF - denoting gains in genes for Kras, Myc, and FAK – we demonstrate the functional significance of PTK2 (FAK) gains observed in HGSOC tumors." (PMID 31478830, 2019). "In drug‐sensitive recurrent ovarian cancer patients, MYC had the highest frequency of copy number variations (3/11, 27%), followed by RB1 (2/11, 18%), and PTK2 (2/21, 10%)." (PMID 29797793, 2018). "Using high-throughput sequencing, we found a circRNA circ-PTK2 that was positively correlated with CHD1L expression, which might be a novel biomarker and therapeutic target for ovarian cancer." (PMID 34034740, 2021). "Here circ-PTK2 expression was upregulated when cell migration and invasion were enhanced, indicating that miR-639 expression was downregulated, while the expression of the corresponding downstream target gene, FOXC1, was upregulated in ovarian cancer." (PMID 34034740, 2021). "Interestingly, proteins such as CCNE1, FASN, HDGF, MCM7, PIGR, PTK2, or TRA2B have been described as having a prognostic relation with some other type of gynecological cancer (breast, cervical or ovarian cancer)." (PMID 34680205, 2021). "Moreover, circ_100395, circFGFR3, circ_0000554, circCELSR1, circ-PTK2, circLNPEP, circ-CSPP1, circ_0000745, circ_100395 and circPLEKHM3 have been shown to regulate epithelial-mesenchymal transition and metastatic ability of ovarian cancer cells." (PMID 35488239, 2022). "However, the occurrence of ovarian cancer and the level of miR-639 and FOXC1 may be regulated by various factors and not just circ-PTK2." (PMID 34034740, 2021).